LDHA (lactate dehydrogenase A)
Diseases named in the same sentence as LDHA in open-access papers (continued):
Sharing a sentence is not in itself a finding about the gene and the disease.
metastatic cancer (3 papers, 2019 to 2023). A carcinoma which has spread from the original site of growth to another anatomic site. "In contrast, the enhanced expression of lactate dehydrogenase A (LDH-A) and lactic acid was observed in our study and this has been associated with aggressive and metastatic cancers in a variety of tumor types." (PMID 31484429, 2019). "In the content of the lactate biosynthesis pathways, over-expression of hexokinase 2 (HK2) and lactate dehydrogenase A (LDHA), the committed steps to regulate magnitude and direction of glucose flux for lactate production, are required for tumor initiation, maintenance, and metastatic cancer spread." (PMID 36986244, 2023).
metastatic colorectal cancer (3 papers, 2010 to 2023). "In previously untreated patients with metastatic colorectal cancer responses to vatalanib plus chemotherapy correlated directly with tissue messenger RNA levels of VEGFR1, LDHA (lactate dehydrogenase A) and Glut1 and inversely with hypoxia-inducible factor 1α (HIF1α1)." (PMID 24281105, 2010).
Parkinson disease (3 papers, 2023 to 2025). A progressive degenerative disorder of the central nervous system characterized by loss of dopamine producing neurons in the substantia nigra and the presence of Lewy bodies in the substantia nigra and locus coeruleus. "The dysregulated expression of LDH isoforms (LDHA/LDHB) and the disruption of the astrocyte–neuron lactate shuttle highlight the central role of metabolic dysregulation in Parkinson’s disease." (PMID 41009388, 2025).
pituitary adenomas (3 papers, 2017 to 2021). "LDHA overexpression promotes cell proliferation and invasion in pituitary adenomas, whereas reduction in LDHA activity compromises the ability of tumor cells to proliferate under hypoxia and severely diminishes tumorigenicity and tumor cell maintenance." (PMID 33714987, 2021). "To further investigate the effect of LDHA on the invasion and proliferation of primary PA cells, we cultured primary cells derived from 4 human invasive pituitary adenomas after transsphenoidal resection." (PMID 28680051, 2017). "Furthermore, as commented above, increased LDHA-mediated glycolysis is related to invasion and proliferation of pituitary adenomas." (PMID 33714987, 2021). "However, the potential role of LDHA in pituitary adenoma (PA) remains unknown." (PMID 28680051, 2017).
psoriasis (3 papers, 2021 to 2023). An autoimmune condition characterized by red, well-delineated plaques with silvery scales that are usually on the extensor surfaces and scalp. "Almost all of the reported patients (14 families to date) showed at least one of the three symptoms characteristic of LDHA deficiency (i.e., myopathy, rhabdomyolysis, or psoriasis-like dermatitis)." (PMID 36292720, 2022). "We have identified two novel nonsense variants associated with LDHA deficiency in two young adult female patients presenting with exercise intolerance, rhabdomyolysis episodes, and psoriasis-like dermatitis (in one case)." (PMID 36292720, 2022). "For this reason, a higher expression of LDHA in lesional epidermis is also necessary due to hyperproliferation and acceleration of the metabolism in epidermal keratinocytes of psoriasis patients." (PMID 34575702, 2021). "According to the previously published data, LDHA is involved in several immunomodulatory processes that could potentially influence the flow of psoriasis." (PMID 34575702, 2021). "In comparison with normal samples, the glycolysis score was significantly higher in psoriasis samples in KRT5+ KRT14+ KC, KRT1+KRT10+ KC, and LDHA+SLC2A1+ KC (all P<0.001)." (PMID 37205116, 2023).
adenoma (2 papers, 2017). A neoplasm arising from the epithelium. "In our study, we initially found that human invasive PA have higher LDHA levels than noninvasive adenomas." (PMID 28680051, 2017). "Pirc rats harboring adenomas/tumors had a significant increase in glycolytic markers in their noninvolved colorectal mucosa compared to Pirc rats without adenomas/tumors, including HIF1α (1.45 fold, p = 0.018), GLUT1 (1.35 fold, p = 0.003), PKM2 (1.33 fold, p = 0.05) and LDHA (1.4 fold, p = 0.003)." (PMID 28423551, 2017).
atherosclerosis (2 papers, 2019 to 2025). A disease characterized by the build-up of fatty material and calcium deposition in the arterial wall resulting in partial or complete occlusion of the arterial lumen. "It has been elucidated that LDHA is essential for the proliferation and migration of VSMCs, and serves as a potential therapeutic target to prevent vessel lumen constriction during the process of atherosclerosis and restenosis." (PMID 31989041, 2019). "In short, the present study indicated that miR-638 could repress the proliferation, migration, invasion abilities and glycolysis of VSMCs by targeting, at least in part, LDHA, which provides a novel potential therapeutic strategy for human vascular diseases, such as atherosclerosis and restenosis." (PMID 31989041, 2019).
autism (2 papers, 2023 to 2025). Persistent deficits in social interaction and communication and interaction as well as a markedly restricted repertoire of activity and interest as well as repetitive patterns of behavior. "Early clinical studies identified that mothers with the combination of LDHA/B+STIP1+CRMP1 autoantibodies had children with a more severe autism phenotype compared to mothers of children with autism who lacked autoantibodies." (PMID 39929953, 2025).
Cirrhosis (2 papers, 2024). A chronic disorder of the liver in which liver tissue becomes scarred and is partially replaced by regenerative nodules and fibrotic tissue resulting in loss of liver function. "The findings of this study indicate that LDHA plays a role in the progression of NAFLD-related cirrhosis to HCC and is linked to an unfavorable prognosis in patients with HCC." (PMID 38993839, 2024). "Next, by screening prognostic models with multiple machine-learning methods and combining the data from single cells, we obtained a crucial gene, LDHA, which is crucial for altered T-cell status in cirrhosis and HCC." (PMID 38993839, 2024). "Additional fundamental research is required to validate the regulatory role of LDHA in the development of cirrhosis in patients with HCC." (PMID 38993839, 2024). "Animal studies confirmed these findings, linking NAC1-mediated LDHA activation to cirrhosis and HCC development." (PMID 38704368, 2024). "Similarly, LDHA in NAFLD-cirrhosis samples was also markedly overexpressed compared to that in the healthy groups (p = 0.045)." (PMID 38993839, 2024). "An in-depth explanation of the potential function of LDHA in the transition from NAFLD-cirrhosis to HCC within the immune microenvironment at the single-cell level remains unclear." (PMID 38993839, 2024). "NAC1, highly expressed in HBV-infected liver cells, likely drives HBV immune escape by activating LDHA expression, inhibiting CD8 + T cells, and promoting cirrhosis and HCC development." (PMID 38704368, 2024).
colitis (2 papers, 2023). Inflammation of the colon. "Colonic expression of glycolysis-associated proteins such as HK2, lactate dehydrogenase A (LDHA), phosphate fructose kinase, and c-MYC are evidently enriched in inflamed tissues of DSS-induced colitis mouse model." (PMID 37809060, 2023).
cutaneous melanoma (2 papers, 2020 to 2025). A primary melanoma arising from atypical melanocytes in the skin. "Accordingly, gene expression analysis in human cutaneous melanomas revealed an inverse correlation between lactate dehydrogenase A (LDHA, the enzyme responsible for LA production) and markers associated with ILC2." (PMID 33329534, 2020).
dental fluorosis (2 papers, 2022 to 2025). A condition that results from excessive fluoride ingestion during tooth development, resulting in tooth discoloration ranging from white streaks to brown stains and cracks or pits in the tooth enamel. "In particular, we noted increased CFTR-linked proteins, such as LDHA, UBA1, implying that the latter may play a role in fluorosis." (PMID 41000239, 2025). "The KGML network diagram showed that the proteins (LDHA, ENO3, GPI, and TPI1) enriched in the HIF-1 and glycolysis/gluconeogenesis pathways have a direct correlation with the formation of dental fluorosis." (PMID 35897842, 2022). "The up-regulation of ENO3, LDHA, TPI1, and GPI implies that the HIF-1 pathway and glycolysis/gluconeogenesis pathway are strengthened in ameloblasts, which affects the energy harvesting of ameloblasts and leads to the formation of dental fluorosis." (PMID 35897842, 2022).
dermatitis (2 papers, 2022 to 2024). An inflammatory process affecting the skin. "Unexpectedly, a significant relationship between dermatitis and the levels of certain insulin-biosynthesis-and-secretion- or insulin-resistance-related polypeptides (GSTO1, FETUA, GSTP1, IGFALS or LDHA) was observed." (PMID 39062477, 2024).
diabetic kidney disease (2 papers, 2022 to 2024). Progressive kidney disorder caused by vascular damage to the glomerular capillaries, in patients with diabetes mellitus. "The glycolysis-associated genes HK2 and LDHA were upregulated in the diabetic kidney organoids, whereas PGC1α (a key regulator of mitochondrial biogenesis involved in diabetic nephropathy) was downregulated." (PMID 35561674, 2022).
Dravet syndrome (2 papers, 2022 to 2023). "Therefore, we took advantage of the use of stiripentol, an antiepileptic drug approved by the FDA for the treatment of Dravet Syndrome, because it also potently inhibits both LDHA and LDHB activity." (PMID 36278433, 2022).
follicular carcinomas (2 papers, 2013 to 2015). "Our results show that ERRα regulates LDH activity by direct interaction with the LDHB promoter in cellular models of follicular thyroid carcinoma, and that PRC may interact with ERRα to decrease LDH activity and modulate the LDHA/LDHB expression ratio." (PMID 23516535, 2013).
Hepatic steatosis (2 papers, 2024 to 2026). Steatosis is a term used to denote lipid accumulation within hepatocytes. "Altogether, these data indicate that targeting hepatic oxalate overproduction in MASH by inhibiting GO and LDHA can be therapeutically utilized to enhance FAO and lower hepatic steatosis." (PMID 39333384, 2024).
Hyperoxaluria (2 papers, 2023). Increased excretion of oxalates in the urine. "Several studies have demonstrated that GO and lactate dehydrogenase (LDHA) influence endogenous oxalate synthesis, a common cause of hyperoxaluria." (PMID 37237348, 2023). "Second, although LDHA can reportedly oxidize glyoxylate into oxalate in vitro, such activity of LDHA has not been confirmed in glyoxylate metabolism in vivo such as under the condition of hyperoxaluria." (PMID 37546420, 2023).
intrahepatic cholangiocarcinoma (2 papers, 2014 to 2025). A carcinoma that arises from the intrahepatic bile duct epithelium in any site of the intrahepatic biliary tree. "FGFR2 inhibition in patient-derived intrahepatic cholangiocarcinoma (ICC) cell lines containing an overactive FGFR2 mutant decreases HK2, PKM2, and LDHA expression." (PMID 39433211, 2025).
invasive ductal carcinoma (2 papers, 2017 to 2020). "We showed significantly higher LDHA and lower LDHB protein expression in malignant tumor tissue than benign tumor tissue, which is a typical signature of luminal type A invasive ductal carcinoma." (PMID 33353120, 2020). "Our present results showed that in a statistical average of 100 cases of invasive ductal carcinoma an increase of some key glycolytic enzymes occurred, namely: ALDOA, G3P KPYM, PGK1, and LDHA, while no relevant increase was observed for other glycolytic enzymes (i.e., ENOA, PGAM1, TPIS)." (PMID 28686225, 2017).
ischemia (2 papers, 2023 to 2024). A hypoperfusion of the BLOOD through an organ or tissue caused by a PATHOLOGIC CONSTRICTION or obstruction of its BLOOD VESSELS, or an absence of BLOOD CIRCULATION. "Lactate from the ANLS involving lactate metabolism-related factors, lactate dehydrogenase A (LDHA), LDHB, and monocarboxylate transporter 4 (MCT4) increases the energy supplied to neurons from astrocytes in protecting against ischemia-induced neuronal death." (PMID 36830049, 2023).
leukoplakia (2 papers, 2023). A white patch or plaque on a mucous membrane that cannot be characterized clinically or pathologically as any other disease. "Across control, leukoplakia, and cancer, L-lactate dehydrogenase A chain, plectin, and WD repeat-containing protein 1 were upregulated, whereas thioredoxin 1 and spectrin alpha chain, nonerythrocytic 1 were downregulated." (PMID 36776920, 2023). "Several studies show that LDHA activity is increased in the serum of patients with leukoplakia and OC,34,35 as well as in the cancer sections of patients, and LDHA has been suggested as a salivary biomarker of OPMD36 and OSCC." (PMID 37194791, 2023).
Lewis lung carcinoma (2 papers, 2019 to 2026). "To evaluate the oncogenic role of LDHA lactylation in vivo, we generated mice Lewis lung carcinoma (LLC) cells with stable LDHA knockdown and complemented them with exogenous overexpression of LDHA‐WT or LDHA‐2KR." (PMID 41190808, 2026). "In mouse models inoculated with murine Lewis lung carcinoma, MA significantly suppressed tumor growth as observed by a reduction of tumor volume and weight; resulting from the inhibition of LDHA activity." (PMID 31324019, 2019). "First, we examined the inhibitory effect of MA on LDHA activity using murine Lewis lung carcinoma LLC." (PMID 31324019, 2019).
liver cirrhosis (2 papers, 2024). "NAC1 mediates HBV immune evasion by transcriptionally activating LDHA, ultimately resulting in the development of liver cirrhosis and HCC." (PMID 38704368, 2024). "In NAFLD, activated T cells have been shown to be closely related to the progression of liver cirrhosis, suggesting that the activation of T cells by LDHA may be part of the reason for the progression of liver cirrhosis." (PMID 38993839, 2024). "Therefore, we speculate that NAC1 mediates its involvement in HBV immune escape, promoting the occurrence and development of liver cirrhosis and HCC by transcriptionally regulating LDHA expression." (PMID 38704368, 2024). "Importantly, NAC1 may facilitate the advancement of liver cirrhosis and HCC by activating LDHA transcription." (PMID 38704368, 2024).
liver failure (2 papers, 2023 to 2024). A liver disease characterized by the liver losing or has lost all of its function. "During liver failure, the metabolism of lactic acid may be closely related to the continuous disorder and sudden outbreak of immune inflammatory response, and the diagnosis and treatment of liver failure targeting lactic acid, such as LDHA and EP, has shown great developmental prospects." (PMID 37724112, 2023). "Other important disease-relevant processes such as liver failure (LCAT, LDHA), complement activation (C3) and tissue damage (MB, H2AC17, ACTB) were also represented by the ML features." (PMID 39681038, 2024).
meningioma (2 papers, 2024). A generally slow growing tumor attached to the dura mater. "Taken together, we demonstrated that CBX7 inhibits LDHA transcription and subsequent glycolysis to protect against meningioma development through the destabilization of c-MYC protein." (PMID 37791390, 2024). "The therapeutical effectiveness of targeting the CBX7/USP44/c-MYC/LDHA axis in meningioma patients needs to be further explored." (PMID 37791390, 2024). "Previous studies reported that c-MYC can directly transactivate the transcription of LDHA gene, which was confirmed in meningioma cells in this study." (PMID 37791390, 2024). "Strikingly, LDHA overexpression significantly accelerated cell cycle progression in CBX7-restored meningioma cells, which was proved by the enriched S/G2 phase population and higher expression of CDK and cyclin proteins." (PMID 37791390, 2024). "Western blot analysis further confirmed the dramatic decrease of LDHA protein expression in CBX7-restored meningioma cells, consistent with the proteomics data." (PMID 37791390, 2024). "As expected, the LDH activity was re-established in CBX7-restored meningioma cells with LDHA overexpression." (PMID 37791390, 2024). "Taken together, our data suggest that targeting glycolysis via inhibiting LDHA can suppress meningioma cell proliferation." (PMID 37791390, 2024). "The EdU incorporation assay and MTS cell proliferation assay further confirmed the retrieved cell proliferation by ectopic LDHA expression in CBX7-restored meningioma cells." (PMID 37791390, 2024). "Collectively, these data supported the functional role of the CBX7/c-MYC/LDHA axis during meningioma progression." (PMID 37791390, 2024). "As expected, c-MYC overexpression successfully rescued the decreased LDHA expression in CBX7-restored meningioma cells." (PMID 37791390, 2024). "More importantly, the role of the CBX7/USP44/c-MYC/LDHA axis is confirmed in human meningioma tissue samples." (PMID 37791390, 2024). "Mechanistically, CBX7 restoration destabilizes c-MYC protein by transcriptionally suppressing USP44 expression and then inhibits the c-MYC-dependent transactivation of LDHA transcription, thus inhibiting glycolysis activity and subsequent cell proliferation in meningioma cells." (PMID 37791390, 2024). "Moreover, LDHA overexpression also rescued the colony formation capacity of CBX7-restored meningioma cells." (PMID 37791390, 2024). "In addition, we only correlated the expression patterns of CBX7, c-MYC, LDHA, and Ki-67 in 445 meningioma patient samples with the follow-up outcomes of these patients." (PMID 37791390, 2024). "Altogether, our results shed light on the critical role of CBX7 in meningioma malignancy progression and identify the CBX7/USP44/c-MYC/LDHA axis as a promising therapeutic target against meningioma progression." (PMID 37791390, 2024). "The measurements of ECAR and OCR further confirmed that the CBX7 restoration-induced metabolic switch from glycolysis to OXPHOS was reversed by the overexpression of LDHA, which suggested that CBX7 restoration forces metabolic switch in meningioma cells via repressing LDHA expression." (PMID 37791390, 2024). "Next, we overexpressed c-MYC in meningioma cells with or without CBX7 restoration to determine the functional role of c-MYC in the CBX7/LDHA axis." (PMID 37791390, 2024). "Importantly, c-MYC directly binds to the LDHA promoter to activate its transcription in malignant meningioma cells, while CBX7 restoration forces the degradation of c-MYC protein and then attenuates c-MYC-mediated transactivation of LDHA transcription." (PMID 37791390, 2024). "First, we only used two representative malignant meningioma cell lines, IOMM-Lee without NF2 mutation and CH157 with NF2 mutation, to explore the regulation and roles of the CBX7/USP44/c-MYC/LDHA axis." (PMID 37791390, 2024).
meningioma (continued). "Although another primary meningioma cell line, HSMN1, was used in the animal model and similar phenotypes were observed, we cannot exclude the existence of other unknown confounders that might affect the conclusion regarding the regulation of the CBX7/USP44/c-MYC/LDHA axis." (PMID 37791390, 2024).
metastasis (2 papers, 2017 to 2021). The spread or migration of cancer cells from one part of the body (where they first appeared) to another. "Besides, high LDHA/PDK1 mRNA was found in OS tumors from patients with shorter overall survival, advanced TNM stages, and lymph node metastasis." (PMID 33962616, 2021).
metastatic melanoma (2 papers, 2012 to 2023). A melanoma that has spread from its primary site to another anatomic site. "Unfortunately, the lack of clinicopathologic annotation makes it impossible to address the significant variability in LDHA expression seen in metastatic melanoma." (PMID 23043612, 2012).